RHO (rhodopsin)
Diseases named in the same sentence as RHO in open-access papers (continued):
Sharing a sentence is not in itself a finding about the gene and the disease.
retinal degeneration (continued). "Thus, it would not be surprising that different mutations in rhodopsin can likewise alter the forms or conformations achieved during aggregation, impacting the retinal degeneration phenotype." (PMID 39875362, 2025). "Thus, neither mislocalization of WT rhodopsin nor retinal degeneration causes the formation of aggregates detectable by PROTEOSTAT in the outer nuclear layer." (PMID 38365903, 2024). "Knock-in Rho-E150K mice were generated to study the mechanisms of rhodopsin-mediated retinal degeneration in an autosomal recessive manner, though it was noted that in contrast to human patients, the heterozygous mouse exhibited a mild and delayed retinal degeneration." (PMID 39556729, 2024). "Specifically, it appears that the vitamin A level plays a role in preventing retinal degeneration, and we hypothesize that the mechanism through which this occurs is stabilization of the constitutively active p.G90D rhodopsin at a higher concentration of 11-cis-retinal." (PMID 36614223, 2023). "Therefore, flavonoids can potentially be used as primary compounds to design nonretinoids for the treatment of retinal degeneration associated with rhodopsin mutations." (PMID 37077319, 2023). "To identify transcriptional changes that occur during chronic retinal degeneration and regeneration, we performed the same type of analysis on a single-cell transcriptome library prepared from the adult retina of a transgenic zebrafish model of retinitis pigmentosa expressing P23H mutant rhodopsin." (PMID 37979052, 2023). "Several therapeutic strategies have attempted to address and counteract the deleterious effect of rhodopsin mutations on the conformation and function of this photoreceptor protein, but none has been successful in efficiently preventing retinal degeneration in humans." (PMID 34069614, 2021). "Although it has been proposed that ERAD may disrupt Rho homeostasis earlier in development and contribute to retinal degeneration, studies in both Drosophila and mouse models suggest that increasing degradation of misfolded rhodopsin through ERAD and the proteasome is protective." (PMID 33137101, 2020). "The chemical chaperone tauroursodeoxycholic acid (TUDCA) has been studied in several retinal degeneration models, although its efficacy was found to vary between different studies, even in the presence of the same IRD-causing mutation, namely p.P23H, in the gene encoding rhodopsin." (PMID 31466352, 2019). "In the present study, we characterized the OCT images during the natural course of retinal degeneration in rhodopsin P23H transgenic rats (line 2) and tried to identify specific relationships between OCT images and photoreceptor degeneration caused by the rhodopsin P23H mutation." (PMID 29522537, 2018). "However, the Tvrm4 degeneration turns into retinal degeneration only as a consequence of interaction of light and rhodopsin and the phenotype might affect only part of the retina." (PMID 28720880, 2017). "Although we had previously found that Tat-μCL protects against retinal degeneration in Mertk mutant RCS rat, the present results revealed that the peptide also exerted protective effects against degeneration in the most prevalent mutations in ADRP, RHO mutants." (PMID 23951212, 2013). "One might, therefore, hypothesize that a significant reduction (between 50%–75%) of WT rod rhodopsin (rod sensitivity reduction by −0.3 to −0.6 log) would not cause rapid retinal degeneration in mammals." (PMID 21785698, 2011). "Interestingly, we observed in a previous study that the rhodopsin mutant, S334ter, did not cause noticeable retinal degeneration in dark-reared mice when it was expressed at 10% of total rhodopsin." (PMID 20532191, 2010). "They found that mislocalized rhodopsin does not require activation to cause retinal degeneration." (PMID 20532191, 2010). "However, as determined in earlier studies, flies carrying this rhodopsin variant do not undergo retinal degeneration." (PMID 19214218, 2009).
retinal degeneration (continued). "Murine models with an increased RHO/PRPH2 ratio exhibited formation of discs with significantly larger diameters than wild type, accelerated retinal degeneration, and decreased physiological function." (PMID 38834544, 2024). "To further analyze the retinal degeneration and damage extent of RPE and photoreceptors under low-dose SI treatment, we examined expression of zonula occludens-1 (ZO1), rhodopsin, and opsin in the SI-treated retinas." (PMID 36018572, 2022). "Here, we utilize two different models of inherited retinal degeneration, the rhodopsin P23H knockin (RhoP23H/+) model of RP and the Prph2 Y141C knockin (Prph2Y141C/+) model of cone-rod dystrophy to evaluate whether eliminating retbindin has broad effects on retinal degeneration." (PMID 33138244, 2020). "Augmented expression of HSP70 in RHOT17M mice, in which mutant rhodopsin is misfolded, marginally improved photoreceptor survival, whereas elevated HSP70 led to more severe retinal degeneration in rd10 mutants that produce a partially functional PDE6B." (PMID 33107904, 2020). "Compared with emc5G2 and emc3G7 null mutant animals, emc6N10 null mutants exhibited lower levels of rhodopsin and TRP proteins, more disrupted rhabdomere morphology, and more severe retinal degeneration." (PMID 31263175, 2020). "In eyes with retinal degeneration after the 1.2-mg or 1.0-mg SI injections, RPE and cone and rod photoreceptor cells were decreased in number based on RPE65, PNA, and rhodopsin staining, respectively." (PMID 32107442, 2020). "A variation in the course of retinal degeneration was noted between C57BL/6 and Sv129S6 mice when examining the effect of rhodopsin knockouts on the retina." (PMID 30778330, 2019). "Eyes with complete changes in retinal degeneration, including those with flat ERG responses, also had less staining with PNA and rhodopsin." (PMID 31666618, 2019). "For example, a KR therapy directed towards rhodopsin was expressed using two separate promoters in an AAV vector and produced phenotypic improvements in a mouse model of retinal degeneration." (PMID 28575281, 2017). "We determined that chrysophanol inhibited the functional and morphological features of MNU-induced retinal degeneration using scotopic electroretinography (ERG), optical coherence tomography (OCT), and immunohistochemistry analysis of R/G opsin and rhodopsin." (PMID 28112220, 2017). "We revealed that a 2.3-fold increase in ATF4 triggers retinal degeneration in wild type mice and mimics conditions with ATF4 over-expression in transgenic T17M rhodopsin retinas." (PMID 29326555, 2017). "The mechanism of retinal degeneration in the ADRP retina includes the impaired assembly of the opsin protein with its chromophore, 11-cis-retinal, and is due to rhodopsin modified stability, folding, and trafficking." (PMID 27144303, 2016). "In our own experimental mouse model (hT17M RHO CHOP−/−), a greater than eightfold increase in peIF2a, a translational inhibitor, was observed with accelerated retinal degeneration." (PMID 24068865, 2013). "In P30 T17M RHO CHOP−/− retinas, this up-regulation most likely leads to transcriptional protein repression and retinal degeneration." (PMID 23646198, 2013). "The RHO gene, therefore, offers a robust model to investigate the extent to which PTGS therapies can be broadly applied as human gene therapies for ad retinal degenerations." (PMID 21785698, 2011). "In rd1 flat-mount retinas, rhodopsin-positive signal was observed at PN19, consistent with incomplete retinal degeneration at this age." (PMID 17563719, 2007). "Rhodopsin (RHO) missense variants are a leading cause of autosomal dominant retinitis pigmentosa (adRP), a progressive retinal degeneration with no currently approved therapies." (PMID 40093169, 2025). "A recent study conducted with rd10 mice demonstrated that light activates a non-canonical pathway in rd10 retinas mediated by rhodopsin, contributing to retinal degeneration." (PMID 38731938, 2024).
retinal degeneration (continued). "Taken together, PROTEOSTAT staining in mice expressing misfolding mutants of rhodopsin appear to reflect the aggregation of misfolded rhodopsin mutants and is independent of retinal degeneration or rhodopsin mislocalization." (PMID 38365903, 2024). "This can be seen in other mouse models with photoreceptor specific mutations (such as peripherin and rhodopsin), which do not have an early RPE phenotype despite retinal degeneration." (PMID 33681195, 2021). "Rho+/− mice exhibit reduced rhodopsin expression in their outer segments but without any overt retinal degeneration at this time point." (PMID 33509952, 2021). "Enhanced TCS is also observed in a second model (rhodopsin heterozygous mice, Rho+/−) with fast rod recovery kinetics and no apparent retinal degeneration." (PMID 33509952, 2021). "In eyes with complete changes in retinal degeneration, H&E staining demonstrated severe disruption of the photoreceptor layer, retinal thinning, and almost complete depletion of the cone and rod photoreceptor cells based on PNA and rhodopsin staining." (PMID 31666618, 2019). "These mice undergo rapid retinal degeneration; prior to which they express low levels of rhodopsin and do not elaborate normal ROS disks." (PMID 28065882, 2017). "Rhodopsin delocalization has been observed in other models of retinal degeneration, but rod photoreceptor debris does not build up in the sub-retinal space of AMD patients as it does in RP disorders that involve RPE processing." (PMID 27199657, 2016). "The present study reveals, for the first time, that dietary supplement containing lutein, zeaxanthin, vitamins C, E, Zinc, omega-3 with mainly EPA and resveratrol protects the retina from light-induced retinal degeneration without affecting rhodopsin." (PMID 26042773, 2015). "On the other hand, norpAP24, rdgC306 and trp1 require light activation of rhodopsin but not subsequent phototransduction for retinal degeneration." (PMID 23754968, 2013). "A beneficial effect on photoreceptor outer segments has also been seen in DHA supplementation of rhodopsin mutant rats, although no alteration in the rate of retinal degeneration was detected." (PMID 24124525, 2013). "Since the T17M rhodopsin increases the pro-apoptotic CHOP protein, we investigated whether the ablation of CHOP in an ADRP retina expressing mutant opsin affects the rate of retinal degeneration." (PMID 23646198, 2013). "We used rdgB2 photoreceptors as a negative control to assume the functions of die4 because cytoplasmic rhodopsin aggregation is not involved in retinal degeneration in rdgB2 photoreceptors." (PMID 23754968, 2013). "Injection of AAV5-XIAP alone at P4 and 21 resulted in significant slowing of light-induced retinal degeneration, as measured by outer nuclear thickness and cell counts, but did not result in improved outer segment structure and rhodopsin localization." (PMID 22615940, 2012). "To follow the localization of P23H-rhodopsin, we used two fluorescent knockin alleles–P23H-hRho-GFP and hRho-GFP–that are expressed at very low levels and do not cause retinal degeneration or interfere with rod cell function." (PMID 23185477, 2012). "On the other hand, most retinal degeneration mouse models, in which the affected gene does not function in rhodopsin or ciliary trafficking, do not show overt opsin mislocalization when the photoreceptor layers are largely still intact." (PMID 23351594, 2012). "Thus, retinal degeneration does not promote the aggregation of non-rhodopsin proteins or any other species that can be stained by PROTEOSTAT." (PMID 38365903, 2024). "Retinal degeneration in crb mutant photoreceptors is strongly attenuated when flies are kept in the dark, or when raised and kept on food lacking vitamin A, a cofactor necessary for functional rhodopsin." (PMID 31834921, 2019).
retinal degeneration (continued). "This might not be the case for other types of rhodopsin RP or other forms of retinal degeneration, where induction of the UPR is a secondary consequence of the disease process, such as those associated with TDP43 alteration in splicing, or PrP aggregation." (PMID 29036441, 2017). "Therefore, the photoreceptor cell death could be hastened in T17M RHO CHOP−/− mice by modified cellular signaling, thus leading to advanced retinal degeneration by 1 month of age." (PMID 23646198, 2013). "Exacerbation of retinal degeneration by light-exposure has been observed for rhodopsin mutants that may or may not initiate a cell death cascade that involves phototransduction." (PMID 20532191, 2010). "Moreover, GFP did not accelerate the course of retinal degeneration in the rhodopsin mouse model in the same study." (PMID 19710944, 2009). "However, mutant mice with targeted disruptions in each of their two PPEF genes show no retinal degeneration and normal rhodopsin dephosphorylation kinetics, suggesting interspecies functional differences despite high similarities in protein sequence." (PMID 17169445, 2007). "Furthermore, in 4-week-old Hbs1ltm1a/tm1a mice, western blotting revealed the remarkable decrease of rhodopsin levels but not of Opn1sw, a cone opsin involved in color vision, indicating that the observed retinal degeneration affects mostly rods but not cones at this time point." (PMID 38966981, 2024). "Although rhodopsin function is thought to be essential for the formation of ROS and phototransduction initiation, heterozygous rhodopsin-knockout mice showed little retinal degeneration, indicating that one copy of this gene is sufficient for normal retinal development and functions." (PMID 37272616, 2023). "Interestingly, the degree of retinal degeneration was similar at p30 and p60 in the presence or absence of Q344ter, indicating that Q344ter mis-trafficking does not accelerate the rate of retinal degeneration in the rhodopsin knockout (rho−/−) background." (PMID 20532191, 2010). "However, the use of the ubiquitous promoter EFs shows that near the injection site some photoreceptors can be transduced suggesting that in the Rho-/- mice the Rhodopsin promoter activity may change during the course of retinal degeneration or that non-detectable cones can be transduced." (PMID 21901134, 2011).
retinitis pigmentosa (150 papers, 2007 to 2026). Retinitis pigmentosa (RP) is an inherited retinal dystrophy leading to progressive loss of the photoreceptors and retinal pigment epithelium and resulting in blindness usually after several decades. "Sakami and colleagues (2011) generated the Rho P23H mouse line, which is now a well-established and extensively used model to study the pathophysiological mechanisms of rhodopsin P23H-associated retinitis pigmentosa." (PMID 41562848, 2026). "Retinitis pigmentosa is a blinding disease that is caused by pathogenic misfolding mutations in the rhodopsin protein." (PMID 39808594, 2025). "Class I rhodopsin mutations are known for some of the most severe forms of vision impairments in dominantly inherited rhodopsin retinitis pigmentosa." (PMID 41056359, 2025). "The purpose of this study was to describe the largest cohort of RHO-associated retinitis pigmentosa (RP) to date, analyzing the spectrum of phenotypes, variants, disease natural history, and genotype-phenotype correlations." (PMID 40736177, 2025). "In the retina, salubrinal enhances photoreceptor survival in the P23H-1 transgenic rat model of retinitis pigmentosa, where mutated rhodopsin misfolding and aggregation lead to ER stress and UPR activation." (PMID 40149812, 2025). "One of the most important known PCDs is retinitis pigmentosa (RP), which is a blinding disease associated with mutations in the rod opsin (RHO) gene among other retina-specific genes." (PMID 39808594, 2025). "Pathogenic mutations that cause rhodopsin misfolding lead to a spectrum of currently untreatable blinding diseases collectively termed retinitis pigmentosa." (PMID 39808594, 2025). "Mutations that disrupt the glycosylation sequence of rhodopsin (RHO) can cause the autosomal dominant form of retinitis pigmentosa (adRP), a blinding retinal disease characterized by gradual degeneration of rod photoreceptors." (PMID 41185951, 2025). "In one form of inherited blinding disease, retinitis pigmentosa, a P23H mutation in the light-sensing receptor, rhodopsin causes rhodopsin misfolding resulting in complete vision loss." (PMID 39361629, 2024). "Our study demonstrates precision genome-editing in an autosomal-recessive form of rhodopsin-associated retinitis pigmentosa." (PMID 39556729, 2024). "The first genetic mutation linked to retinitis pigmentosa (RP) was the P23H-rhodopsin mutation, causative for autosomal dominant RP (adRP)." (PMID 39556729, 2024). "Rhodopsin is a photosensitive G-protein-coupled receptor (GPCR) found in rod cells for detecting light/dark contrast, and mutations in the rhodopsin gene contribute to various retinal degenerative diseases such as retinitis pigmentosa." (PMID 38790708, 2024). "The RHO gene, which encodes rhodopsin, is linked to retinitis pigmentosa (RP) and is associated with photoreceptor degeneration." (PMID 39439625, 2024). "Transgenic pigs have been developed as models for some forms of retinitis pigmentosa due to RHODOPSIN (RHO) mutations (Pro23His, Pro347Ser112, and Pro347Leu mutations) and Stargardt disease caused by ELOVL4 mutations." (PMID 37288665, 2023). "Mutations in rhodopsin not only lead to rod death in retinitis pigmentosa, but cones also eventually die." (PMID 37745292, 2023). "In the context of retinitis pigmentosa, the frequently diagnosed rhodopsin P23H mutation causes rhodopsin misfolding and accumulation in the endoplasmic reticulum." (PMID 37123404, 2023). "Zelinka, Sotolongo-Lopez & Fadool (2018) produced a transgenic zebrafish with a specific mutation in the gene encoding the visual pigment rhodopsin (RHO), which is a common cause of retinitis pigmentosa (RP)." (PMID 36982479, 2023). "This manuscript addresses the mouse phenotype of the F45L rhodopsin mutation that has been previously loosely associated with retinitis pigmentosa and in vitro defects in rhodopsin dimerization." (PMID 36823167, 2023).